INS (insulin)
Diseases named in the same sentence as INS in open-access papers (continued):
Sharing a sentence is not in itself a finding about the gene and the disease.
type 1 diabetes (continued). "For instance, empagliflozin monotherapy was found not to reduce postprandial glucose excursions or 24-h glucose variability, while when added to insulin therapy empagliflozin significantly lowered glucose excursions in type 2 and even in type 1 diabetes." (PMID 33195459, 2020). "The majority of individuals with WRS in the DPV registry were on insulin pump therapy (90%), which is the preferred mode of insulin delivery for paediatric patients with type 1 diabetes aged < 7 years." (PMID 32321554, 2020). "Individuals with type 1 diabetes can have normal levels of muscle and liver glycogen content if they are adequately fed, take insulin and have good glycaemic control (HbA1c <58 mmol/mol [7.5%])." (PMID 32533229, 2020). "The main purpose of these digital therapeutic devices has been to treat patients with type 1 diabetes with a device that injects insulin or glucagon subcutaneously based on continuous measurement of blood glucose." (PMID 32509974, 2020). "Type-1 diabetes is characterized by high blood glucose levels due to a failure of insulin secretion from beta cells within pancreatic islets." (PMID 32325974, 2020). "The number of pancreatic α-cells increased under conditions of insufficient insulin, due to damage to β-cells, as found in patients of recent-onset type 1 diabetes and STZ-induced diabetic animals." (PMID 33553143, 2020). "A similar assay was used to detect human norovirus-specific antibodies or autoantibodies directed against proinsulin/insulin, which is important for diagnosis of type 1 diabetes." (PMID 33050422, 2020). "One subject was treated with insulin for type 1 diabetes and one subject had a history of childhood asthma." (PMID 30478523, 2020). "People with Type 1 diabetes, therefore, need to make carefully calculated changes in insulin dosage and nutritional intake in line with the normal expected physiological responses to the particular exercise and intensity they are performing." (PMID 31265147, 2020). "Type 1 diabetes is an autoimmune disease whereby components of insulin-secreting pancreatic beta cells are targeted by the adaptive immune system leading to the destruction of these cells and insulin deficiency." (PMID 32314012, 2020). "The metabolic consequence of type 1 diabetes (T1D) is a severe reduction of endogenous insulin capacity, leading to the inability to control blood glucose levels." (PMID 31971833, 2020). "Randomized controlled trials investigating the effect of exercise compared to rest on insulin absorption in people with type 1 diabetes or healthy individuals." (PMID 33193089, 2020). "Repeated administration of tolerogenic peptides from the insulin molecule has been successful in reducing HbA1c and insulin requirements in newly diagnosed adults with type 1 diabetes." (PMID 32845332, 2020). "Focusing on the retina, studies have shown altered insulin signaling in the Streptozotocin (STZ) model of type 1 diabetes." (PMID 32432228, 2020). "Type 1 diabetes (previously known as insulin-dependent, juvenile, or childhood-onset) is characterized by deficient insulin production and requires daily administration of insulin." (PMID 32724304, 2020). "A high level of ketones in the blood is observed in patients with Type 1 diabetes who are insulin dependent." (PMID 32106464, 2020). "Plasma Arg concentrations comparable to our CF patients were also observed in pediatric diabetes type I patients under long-term insulin treatment." (PMID 32604946, 2020). "Concern about hypoglycaemia is a barrier to optimal diabetes care, and severe hypoglycaemia is the most serious adverse effect of insulin therapy in patients with type 1 diabetes." (PMID 32704570, 2020). "In type 1 diabetes (T1D), autoreactive cytotoxic CD8+ T cells are implicated in the destruction of insulin‐producing β cells." (PMID 31660582, 2020).
type 1 diabetes (continued). "Generating insulin-producing β-cells from human induced pluripotent stem cells is a promising cell replacement therapy for improving or curing insulin-dependent diabetes." (PMID 32161757, 2020). "Type 1 diabetes (T1D) is one of the most common autoimmune diseases which is characterized by the destruction of insulin-producing β cells by autoreactive T cells." (PMID 32878069, 2020). "Unlike other irAEs where glucocorticoids are the mainstay of therapy, type 1 diabetes is primarily treated with insulin." (PMID 32733645, 2020). "High temperatures are known to increase respiratory morbidity, and to affect insulin therapy for type 1 diabetes patients." (PMID 33049930, 2020). "Hypoglycemia is the most common side effect of insulin therapy in type 1 diabetes (T1D) and its frequency increases with tight glucose control." (PMID 32204318, 2020). "Type 1 diabetes (T1D) is largely considered an autoimmune disease leading to the destruction of insulin-producing pancreatic β cells." (PMID 33193091, 2020). "We and others have previously demonstrated that Abn-CBD can directly stimulate insulin secretion in vitro as well as in vivo in a mouse model of mild type 1 diabetes." (PMID 32210914, 2020). "People with type 1 diabetes (T1D) need specific treatment, including insulin therapy and advice on physical activity and medical nutrition therapy to ensure optimal self-management of the disease." (PMID 31906543, 2020). "Because insulin levels cannot immediately be lowered at exercise onset, individuals with type 1 diabetes are often hyperinsulinaemic during their activity." (PMID 32533229, 2020). "The artificial pancreas (AP) is a system intended to control blood glucose levels through automated insulin infusion, reducing the burden of subjects with type 1 diabetes to manage their condition." (PMID 32399164, 2020). "Even in those with a clear diagnosis of type 1 diabetes, there is increasing evidence that confirming endogenous insulin secretion has clinical implications." (PMID 32034440, 2020). "Type 1 diabetes (T1D) is an autoimmune disease resulting from the destruction of insulin-producing pancreatic β-cells." (PMID 32457759, 2020). "Type I Diabetes (T1D) is an auto-immune disorder that results from T cell-mediated destruction of the insulin-producing β cells of the pancreatic islets." (PMID 32821932, 2020). "Insulin requirements of individuals with WRS registered in DPV appear to be comparable to those of preschool children with well-controlled type 1 diabetes, while glycaemic control tends to be worse and episodes of SH tend to be more common." (PMID 32321554, 2020). "Avoidance of severe hypoglycemia for 2–3 weeks can reverse impaired awareness of hypoglycemia, which is difficult to achieve in practice with current intensive insulin treatment in children with type 1 diabetes." (PMID 33042005, 2020). "Type 1 diabetes is an autoimmune disease ultimately resulting from the destruction of the insulin-producing β-cells of the pancreas by autoreactive T cells." (PMID 32983158, 2020). "In a study in type 1 diabetes, subjects needed 17.5% more U-300 than U-100 insulin glargine for the same glycemic control." (PMID 32396624, 2020). "Nearly 100 years after its first clinical use, insulin remains the primary treatment of type 1 diabetes (T1D)." (PMID 32789003, 2020). "Pancreatic islet transplantation is a promising treatment option for patients with type 1 diabetes that restores both endogenous insulin production and glycemic stability." (PMID 33034128, 2020). "Type 1 diabetes is an autoimmune disorder identified by the destruction of the β-cells of pancreas and impaired secretion of insulin." (PMID 32815547, 2020). "With the exception of insulin, all major targets of autoantibodies in type 1 diabetes are expressed outside of the insulin-producing beta cell, typically in cells of neuroendocrine origin." (PMID 32314012, 2020).
type 1 diabetes (continued). "Type 1 diabetes is an autoimmune disease resulting in the destruction of pancreatic insulin-secreting beta cells." (PMID 31980846, 2020). "Either way, this phenomenon seems like the opposite of the honeymoon period in type 1 diabetes, where there is frequently a transient improvement in islet cell function and insulin secretion in the months following initial insulin therapy." (PMID 32300791, 2020). "Magnetic resonance spectroscopy measurements in humans revealed a decrease in glutamate in healthy control and type 1 diabetes (T1D) patients exposed to 30 min of insulin-induced hypoglycemia." (PMID 32214088, 2020). "AI-401 is a recombinant insulin formulation developed using oral tolerance therapy, which suppresses autoreactive T cells in type I diabetes mellitus." (PMID 33352795, 2020). "For individuals with type 1 diabetes (T1D) in East Africa and other low‐income regions, the last decade has seen substantial gains in access to insulin and trained healthcare providers, yet metabolic control remains poor." (PMID 32704558, 2020). "Type 1 diabetes (T1D) is a chronic condition in which the pancreatic beta-cells either stop or reduce drastically the production of insulin." (PMID 32399164, 2020). "This in vivo study has demonstrated that the IMAP effectively delivers insulin and produces robust hypoglycemic effects in a type-1 diabetic rat model, with more advanced controllability and efficiency than delivery by a pristine microneedle or iontophoresis." (PMID 34567719, 2020). "Type 1 diabetes arises from the autoimmune destruction of insulin-producing beta-cells of the pancreas, resulting in dependence on exogenously administered insulin to maintain glucose homeostasis." (PMID 33154504, 2020). "Insulin-dependent or type I diabetes mellitus depends totally on insulin replacement therapy as the therapeutic strategy." (PMID 33291236, 2020). "Millions of adults are estimated to be living with type 1 diabetes and are dependent on exogenous insulin to regulate blood glucose levels." (PMID 32746937, 2020). "Currently, all people with type 1 diabetes in Scotland receive education on insulin management during sickness and are provided with meters for measuring ketones." (PMID 32451572, 2020). "Intravenous fluids and insulin are critical for the management of DKA with subcutaneous insulin as the mainstay outpatient treatment for type 1 diabetes." (PMID 32733645, 2020). "Our data revealed that butyric acid can mediate Ffar2 to increase blood insulin in STZ-induced type 1 diabetic mice." (PMID 32404878, 2020). "Type I diabetes mellitus (T1DM) is an autoimmune disease, which mainly leads to the apoptosis of islet β cells and the absolute deficiency of insulin." (PMID 32265719, 2020). "Very recently, we investigated the effect of glycemic control on a wide array of immune parameters in insulin-treated persons with type 1 diabetes." (PMID 32626786, 2020). "The number of EPCs is reduced in patients with chronic heart failure stroke insulin-dependent and non-insulin-dependent diabetes rheumatoid arthritis and chronic renal failure." (PMID 33218322, 2020). "Many patients with Type 1 diabetes control their blood glucose levels by injecting insulin several times daily because of the poor therapeutic options currently available." (PMID 32887316, 2020). "Injectable insulin is the most widely used therapy in patients with type 1 diabetes which has several disadvantages." (PMID 32695298, 2020). "In models of type I diabetes, the immune cells infiltrate the islets and kill the insulin-producing beta cells." (PMID 33158929, 2020). "Nevertheless, glucose homeostasis simulators have been proven helpful to test algorithms for optimal insulin administration regimens in type 1 diabetes, based on continuous glucose monitoring or the artificial pancreas." (PMID 33324238, 2020).
type 1 diabetes (continued). "A recent clinical trial demonstrates that liraglutide reduced HbA1c and insulin requirements in patients with long-standing type 1 diabetes." (PMID 32477262, 2020). "In individuals with type 1 diabetes, circulating insulin levels depend on the amount and location of insulin administration." (PMID 32533229, 2020). "Type 1 diabetes is an autoimmune disease, an attack by the immune system on insulin-producing islet cells." (PMID 31971833, 2020). "The current pharmacological treatment of Type I diabetes involves administration of exogenous insulin in response to blood glucose levels." (PMID 33282827, 2020). "Several studies showed that human and mouse beta EV contain major auto-antigens of type 1 diabetes such as glutamic acid decarboxylase 65 (GAD65), glucose-transporter 2 (GLUT-2), islet-associated antigen 2 (IA-2), zinc transporter 8 (Znt8), and insulin." (PMID 33101266, 2020). "Type 1 diabetes is characterized by activation of T lymphocytes and distinguished from type 2 (non-insulin-dependent diabetes) by the presence of autoantibodies, insulin dependence, genetic background, and insulitis." (PMID 32566684, 2020). "Clinical studies have shown that a significant proportion of people with type 1 diabetes continue to secrete insulin for many years beyond diagnosis, although this is rare in children diagnosed <7 years." (PMID 32172310, 2020). "The uptake of continuous subcutaneous insulin infusion (CSII) therapy in those with type 1 diabetes varies internationally and is mainly determined by the national healthcare reimbursement systems." (PMID 32576284, 2020). "Intensified insulin regimen through both multiple daily insulin injections and continuous subcutaneous insulin infusion have been proven effective in achieving near-euglycemia in type 1 diabetes (DM1)." (PMID 32695233, 2020). "For insulin-dependent type-I diabetics, continuous subcutaneous insulin infusion (CSII) pumps allow for effective and passive insulin therapy for type-I diabetes." (PMID 32785196, 2020). "In human subjects, differences in glucose threshold for insulin (C‐peptide) secretion was evaluated in individuals recently diagnosed for type 1 diabetes and compared to control subjects." (PMID 32618430, 2020). "One strength of our large, retrospective study is that we were able to distinguish between patients with insulin-dependent and non–insulin-dependent diabetes from the birth certificate data." (PMID 33408574, 2020). "Immunohistological analysis was used to determine the distribution of proinsulin and insulin in the islets of pancreas samples recovered soon after type 1 diabetes onset (<2 years) from young people diagnosed at age <7 years, 7–12 years and ≥13 years." (PMID 32172310, 2020). "Our institution (University of Cincinnati College of Medicine; Cincinnati, Ohio) historically required all patients with a new diagnosis of type 1 diabetes to be admitted for insulin management and education." (PMID 32125428, 2020). "The administration of insulin to animals with type I diabetes leads to an increase in the expression level of mitochondrial proteins and an improvement of energy metabolism (an increase in the rate of ATP synthesis)." (PMID 32911736, 2020). "Type 1 diabetes is a common autoimmune disease due to destruction of pancreatic β cells, resulting in lifelong need for insulin." (PMID 32399500, 2020). "Future work is required to determine if GLP-1 mediates the Ffar2-butyric acid induced insulin secretion in the STZ-induced type 1 diabetic mouse model." (PMID 32404878, 2020). "Type I diabetes mellitus is now efficiently treated by insulin injection, while type II one requires long-term treatments, and thereby comorbid abnormal pain would be more problematic." (PMID 32824296, 2020). "This study aims to develop a personalized health model that can automatically detect the incidence of infection in people with type 1 diabetes using blood glucose levels and insulin-to-carbohydrate ratio as input variables." (PMID 32784179, 2020).
type 1 diabetes (continued). "For almost 100 years, patients with type 1 diabetes mellitus (T1D) have been given “palliative” treatment with insulin." (PMID 32111075, 2020). "The study assessed changes in insulin/carbohydrate ratio (I:CHO) after the first 6 months of degludec therapy in a paediatric population with type 1 diabetes previously treated with glargine U100." (PMID 32318639, 2020). "People with type 1 diabetes lose the ability to produce insulin after their immune system attacks the β-cells in their pancreas that make this hormone." (PMID 33164744, 2020). "Discoveries such as the use of injectable insulin in the 1920s and the development of at-home monitoring tools (ie, glucometer) in the 1970s revolutionized care for patients with type 1 diabetes." (PMID 32125428, 2020). "We found that STZ rats showed typical features of type 1 diabetes, manifested as low insulin levels and high glucose levels in the plasma." (PMID 32001956, 2020). "Insulin application and blood glucose control is the standard therapeutic methods for type 1 diabetes." (PMID 32771052, 2020). "Carbohydrate counting allows individuals with type 1 diabetes to match their insulin doses to planned food consumption, and accurate carbohydrate counting can improve blood glucose control (measured by hemoglobin A1c; HbA1c)." (PMID 33112249, 2020). "For example, many people with type 1 diabetes use continuous glucose monitors and insulin pumps, which are predicted to grow further in terms of both quality and quantity of data in the coming years." (PMID 32784178, 2020). "Type 1 diabetes (T1D) mellitus is characterized by immune-mediated destruction of insulin-producing β-cells in the pancreatic islets." (PMID 33336012, 2020). "Intensive insulin therapy in type 1 diabetes often increases body fat stores and body weight, although this effect can be attenuated with dietary restriction and/or endurance training." (PMID 32533229, 2020). "Type 1 diabetes (T1D) is a disease thought to result from an autoimmune attack damaging the beta cells in the pancreas, which leads to an insufficiency in insulin production." (PMID 32697399, 2020). "The current study was designed to characterize the CRR actions of ghrelin during insulin-induced hypoglycemia in the setting of type 1 diabetes." (PMID 33042003, 2020). "The UVa/Padova is a simulator for Type I Diabetes Mellitus Patients, and for this reason it lacks any functional representation of the insulin secretion mechanism." (PMID 32797106, 2020). "Type 1 diabetes (T1D) is a T cell-mediated autoimmune disease in which the pancreatic insulin-secreting beta cells are selectively destroyed." (PMID 33469446, 2020). "In the case of type 1 diabetes (T1D), insulin is a primary target antigen during disease development and thus, also for tolerance induction to prevent disease onset." (PMID 33193362, 2020). "In general, athletes with type 1 diabetes perform training and competition with elevated circulating insulin levels and blunted glucagon responses that typically require a high rate of carbohydrate consumption in race events." (PMID 32533229, 2020). "Type 1 diabetes mellitus (T1DM) is an autoimmune disease characterized by the gradual destruction of insulin-secreting beta cells in pancreatic islets." (PMID 33284818, 2020). "A large European cohort of individuals with LADA who were not treated with insulin at diagnosis showed four genetic signals that achieved genome-wide significance at established type 1 diabetes risk loci (HLA, PTPN22, INS and SH2B3)." (PMID 31813006, 2020). "Among these factors, insulin administration remains the cornerstone of type 1 diabetes management, but its optimal dosing is often complicated by the need to count carbohydrates." (PMID 33112249, 2020). "Type 1 diabetes (T1D) is characterized by uncontrolled hyperglycemia resulting from autoimmune-mediated destruction of insulin-producing beta cells." (PMID 33552063, 2020).